INS (insulin)
Diseases named in the same sentence as INS in open-access papers (continued):
Sharing a sentence is not in itself a finding about the gene and the disease.
diabetes (continued). "Diabetes self-management skills training enables patients to adapt insulin doses on a daily basis, in order to accommodate increased dietary freedom." (PMID 24511312, 2014). "Alloxan, a β-cytotoxin, induces diabetes by damaging insulin secreting β cell of the pancreas, resulting in decreased endogenous insulin release." (PMID 24944826, 2014). "Insulin is a glucose-lowering hormone secreted from the pancreatic -cells in response to raised plasma glucose levels, and it is now well-established that defective insulin secretion plays a pivotal role in the development of diabetes." (PMID 24391482, 2014). "This technique represents a promising strategy to promote the intestinal absorption efficiency and release behavior of the hormone, potentially enabling an efficient and safe route for oral insulin delivery of insulin in diabetes management." (PMID 24833901, 2014). "The benefit of physical activity for children and adolescents with diabetes includes better blood glucose control and enhanced insulin sensitivity." (PMID 24867418, 2014). "Experiments in which VF was extracted from 20-month-old Fischer 344 Brown Norway (FBN) rats prevented the progressive decrease in insulin action and delayed the onset of diabetes." (PMID 25118634, 2014). "This group is characterized by progression to insulin-requiring diabetes, lower C-peptide levels and usually lower body mass index (BMI) in younger subjects (e.g. 45 years of age)." (PMID 25226365, 2014). "Rosiglitazone is known for its ability to improve insulin sensitivity and has been used extensively in patients with non-insulin-dependent diabetes mellitus." (PMID 25144187, 2014). "With this background present study was designed to observe the effect of exogenous insulin on the gross morphology of placenta, fetal and maternal outcomes in gestational diabetics in our setting." (PMID 24772119, 2014). "One patient with a large amount of food residue had type 2 diabetes mellitus that was being treated with insulin therapy." (PMID 24968310, 2014). "We then assessed the effects of an insulin-mimetic flavonoid, biochanin A, in treatment of rats with type 2 diabetes mellitus and on circulating visfatin levels." (PMID 25593725, 2014). "According to a Cochrane review, recombinant human insulin is the insulin of choice for new cases of diabetes mellitus." (PMID 25259517, 2014). "Type 1 diabetes mellitus (T1DM) is a chronic autoimmune disease in which insulin-secreting pancreatic β cells are destroyed by autoreactive T cells." (PMID 24594640, 2014). "As expected, animals treated with S961 developed diabetes (reaching blood glucose levels ≥460 mg/dl) and show an increase in insulin staining, while Ucn3 staining was almost completely abolished." (PMID 25233132, 2014). "The plants known as “pedra-hume-caá” or insulin plants have been used for the treatment of diabetes according to the empirical African and indigenous knowledge that influenced the formation of the Brazilian culture." (PMID 24872834, 2014). "All secondary hospitals can treat hypertension, cervical cancer and diabetes patients who require insulin." (PMID 25005125, 2014). "In the author’s clinic, children and adolescents who display multiple risk markers for dysglycemia (prediabetes or diabetes) undergo a basic two-hour oral glucose tolerance test (OGTT) with fasting and 2-hour blood samples for glucose and insulin." (PMID 25241606, 2014). "Compared to cross-sectional studies of the diabetes population, the current study included a relatively high proportion of insulin-treated patients (49.7%)." (PMID 25100190, 2014). "This condition has been particularly described among the adolescent population, as weight management during this time of development for individuals with diabetes can be particularly difficult forcing them to restrict or omit insulin." (PMID 24885411, 2014).
diabetes (continued). "After being treated with standard therapy for insulin-dependent diabetes mellitus (insulin) for more than 20 years, a 49-year-old white man affected by insulin-dependent diabetes mellitus adopted the standard therapy aminaphtone for a period of 2 months." (PMID 25524258, 2014). "Linagliptin, a potent and selective inhibitor of DPP-4, improves glucose homeostasis in patients with diabetes by blocking the degradation of incretins and thus improving insulin secretion in a glucose-dependent manner." (PMID 24906949, 2014). "The first stage of pre-diabetes involves a long period of insulin resistance accompanied by a compensatory increase in pancreatic insulin secretion and increased beta cell mass." (PMID 24824753, 2014). "Most of these, however, suffer from the disadvantage that the insulin secretory defect cannot be reversed, either because the diabetes is genetic or is artificially induced by β-cell ablation." (PMID 25145789, 2014). "The involvement of TG2 in the regulation of insulin secretion and diabetes mellitus has also been suggested." (PMID 24778599, 2014). "Rat insulin promoter-GP34-20 (RIP-GP34-20) transgenic mice were used for rapid onset IDDM (insulin dependent diabetes mellitus) and RIP-NP 25-3 mice were used for slow onset IDDM." (PMID 26556194, 2014). "Hyperglycemia, hypoinsulinemia, and the trophy of pancreatic islets and the depletion of insulin contents are the obvious signs of STZ diabetes." (PMID 24842144, 2014). "The peroxisome proliferator-activated receptor-gamma (PPARy) agonist, pioglitazone, belongs to the insulin-sensitizing group of drugs, which is used in the treatment of type 2 diabetes mellitus (T2DM)." (PMID 26171320, 2014). "The average duration of diabetes was 6.0 (±6.0) years, with 9.3 (±6.8) for the insulin-experienced group and 5.0 (±5.4) for the insulin-naïve group." (PMID 25424627, 2014). "FOXO6 becomes deregulated in the insulin-resistant liver, accounting for its enhanced activity in promoting gluconeogenesis and correlating with the pathogenesis of fasting hyperglycemia in diabetes." (PMID 24864265, 2014). "In the multivariate analysis, a significant effect of the interaction between diabetes duration, insulin therapy, and the presence of DR was found for both, ADDQoL and DTSQ." (PMID 25138117, 2014). "The other study analyzed the interaction between the cryptochrome 1 (Photolyase-Like) (CRY1) rs2287161 SNP and 4 diabetes-related traits (fasting glucose and insulin, HOMA-IR index and QUICKI index)." (PMID 25421534, 2014). "These parameters indicate that the enrolled patients had relatively long duration of diabetes, relatively high frequency of obese subjects, high frequency of insulin use, and high dosage of insulin." (PMID 25237400, 2014). "Prior to the availability of insulin, people who developed diabetes before the age of 30 died within an average of 1.4 years of disease onset." (PMID 25426948, 2014). "Among patients with diabetes, 27 were treated with oral hypoglycemic agents (OHAs), and seven with insulin either alone or in combination with OHAs." (PMID 25139960, 2014). "The three most popular apps chosen by reviewers each offered a different function: Diabetes Logger (n=25)m a data recording app; You + Your Diabetes (n=24), a notes/ agenda setting app; and Insulin Calc (n=17), an insulin dose calculator app." (PMID 25654312, 2014). "Insulin sensitivity is a key cellular mechanism related to diabetes, cerebrovascular dysfunction, and cognitive decline." (PMID 24860814, 2014). "In fact, the discontinuation group in the present study had a longer duration of diabetes (mean 14 years), higher baseline HbA1c (mean 8%, 64 mmol/mol), and higher baseline insulin dose (mean 29 U/day) than the continuation group." (PMID 24578756, 2014).
diabetes (continued). "The interactive educational Diabetes/Insulin Tutorial at the AIDA website demonstrates how AIDA online can be integrated with “static” informational material to provide an even more engaging educational resource." (PMID 24511312, 2014). "Similar rates of INS resistance and diabetes occur as a result of OHSS in which E2 concentrations often exceed 10 nM." (PMID 25101056, 2014). "Several times a day, they have to monitor the blood glucose level, administer insulin, regulate food intake, and guard these parameters in conjunction with the level of physical activity of their child with diabetes." (PMID 24915962, 2014). "T1D was defined according to the American Diabetes Association, and by positive autoantibodies to GAD, insulin, and/or IA2." (PMID 25358866, 2014). "Our analysis focused on longstanding diabetes and we found higher frequencies of insulin positive MMc compared with the recent onset case reported previously by Nelson and colleagues." (PMID 24498006, 2014). "There were 243 patients with diabetes (including 50 patients treated with insulin) among BIMA patients." (PMID 25238877, 2014). "Prevalence of diabetes in the French population is estimated at 6%, including patients treated with oral antidiabetic medications and/or insulin (4.4%), patients treated with diet alone (0.6%) and individuals with undiagnosed diabetes (1%)." (PMID 24555698, 2014). "And two diabetes-related metabolic pathways—insulin signaling pathway and IGF signaling pathway, were regulated." (PMID 24701242, 2014). "Altogether, these observations, in conjunction with our results, suggest the need for careful consideration when treating type 2 diabetes mellitus with insulin, especially when insulin levels are already elevated." (PMID 24949486, 2014). "In diabetes mellitus because of the absence or insufficient sensitivity to insulin, glucose transporter protein in cell membrane, glucose transporter 4, is decreased." (PMID 24719730, 2014). "At this point, Callum stopped talking about being able to control his own diabetes with tablets and diet, suggesting that “sooner or later, it’s going to become an insulin issue”." (PMID 25127714, 2014). "Type 1 diabetes mellitus is a result of autoimmune destruction of pancreatic insulin producing β-cells and so far it can be cured only by insulin injection, by pancreas transplantation, or by pancreatic islet cells' transplantation." (PMID 25405207, 2014). "Insulin treatment can improve glycaemic control, prevent the development of long-term complications of diabetes, and influence patients’ quality of life." (PMID 25424627, 2014). "Premixed insulin regimens are commonly used for the treatment of patients with type-2 diabetes mellitus (T2DM)." (PMID 24620742, 2014). "Diabetes is characterized as hyperglycemia resulting from a relative or absolute impairment of insulin secretion as well as peripheral resistance to insulin." (PMID 24885568, 2014). "The majority of oral medications in the list generated by that study fell into the categories of antibiotics, analgesics, anti-emetics, diabetes treatment (metformin and insulin), and psychiatric medications (primarily antidepressants)." (PMID 24575394, 2014). "In Bulgaria, a Diabetes Education Program was designed in 1997 to introduce a large-scale unified structured educational program for insulin-treated diabetic patients." (PMID 25278037, 2014). "Most previous studies found that duration of diabetes, insulin treatment, proteinuria, and presence of retinopathy are factors associated with DPN, and our results are consistent with these findings." (PMID 24789071, 2014). "The results were consistent with the theory that basal insulin adjustment using CSII therapy in patients with diabetes provides less variable blood glucose levels than long-acting insulin." (PMID 25187822, 2014).
diabetes (continued). "Type 2 diabetes mellitus is a progressive disease characterized by an impairment of insulin action and failure of pancreatic β-cells to compensate for the enhanced insulin demand." (PMID 24772450, 2014). "Production of a sufficient number of insulin-producing cells from stem cells that function similarly to primary islets is important for clinical application of stem cell therapy to diabetes." (PMID 24886514, 2014). "Impaired insulin secretion contributes to the pathogenesis and pathophysiology of diabetes and is a target for its treatment." (PMID 25373904, 2014). "The HMW adiponectin has been the active form of the hormone and has relevant role in enhancing insulin sensitivity and in protecting against diabetes." (PMID 24650537, 2014). "Inhalable nanoparticles composed of glycol chitosan, chitosan-coated PLGA, or polybutylcyanoacrylate also have sustained-release characteristics for calcitonin, insulin, and exendin-4, and prolonged therapeutic effects in osteoporosis and diabetes." (PMID 25302615, 2014). "The PANDAs (Patients ANd Decision Aids) Trial evaluated a PDA for patients with diabetes facing decisions about treatment options, including insulin, in a primary care setting (NIHR National Trials Register Number 14842077)." (PMID 24908099, 2014). "There is alarming and widespread poor knowledge of insulin use among Nigerian insulin requiring diabetes patients." (PMID 24397956, 2014). "Up to date, no data are available to answer the question if cystic fibrosis related diabetes should always initially be treated by insulin therapy." (PMID 24620855, 2014). "In the subset of individuals who had a second liver biopsy, only those that had remission of diabetes and improvement in insulin sensitivity had an increase in liver ENPP1 protein abundance." (PMID 25539584, 2014). "DNEs expressed that their skills in diabetes education, insulin initiation and titration were superior to other health professional groups, and this was reinforced by all groups, especially specialist physicians." (PMID 24479762, 2014). "Patients were identified to include any outpatient diabetes diagnosis (ICD-9: 250), and drug prescriptions that included any oral hypoglycemic agents or insulin prescribed during the 6 months following their first outpatient visit for diabetes." (PMID 25347712, 2014). "Glutamate production is diminished in an incretin-unresponsive, insulin-secreting β cell line and pancreatic islets of animal models of human diabetes and obesity." (PMID 25373904, 2014). "Some parents tried to warn their children about the effects of having diabetes and having to take insulin shots daily." (PMID 25538931, 2014). "While insulin therapy is key part in management of type 1 diabetes, other types of diabetes mellitus require insulin therapy in its management depending on the balance between insulin secretion and insulin resistance." (PMID 24397956, 2014). "Type 2 diabetes mellitus (T2DM) is characterized by a progressive reduction in β-cell secretion of insulin and mass together with insulin resistance." (PMID 25187822, 2014). "We conclude that insulin and mTORC1 regulate cardiac miR-29-MCL-1 axis and its dysregulation caused by reduced insulin and mTORC1 inhibition increases the vulnerability of a diabetic heart to structural damage." (PMID 25062042, 2014). "Hyperglycemia impairs insulin secretion as well as insulin action, being recognized as the glucotoxicity that accelerates diabetes." (PMID 24704640, 2014). "Diabetes mellitus is a highly prevalent illness and a number of diabetic patients require treatment with subcutaneous insulin injections." (PMID 25009591, 2014). "In terms of insulin secretion, it is difficult to distinguish between adult type 1 diabetes mellitus and LADA." (PMID 24711923, 2014). "The score incorporates simple variables such as the presence of metabolic syndrome and type 2 diabetes mellitus, fasting serum insulin, AST level and AST/ALT ratio." (PMID 25937854, 2014).
diabetes (continued). "Six patients (40 %) had postoperative diabetes; five patients required insulin administration, and one patient was free from insulin." (PMID 24883129, 2014). "Diabetes, 90% of which is type 2 diabetes (T2D), is characterized by impaired glucose homeostasis and decreased insulin activity and insulin resistance, which lead to elevated blood glucose levels and multiple system complications." (PMID 25361902, 2014). "Only six studies provided the diabetes duration and four papers stated that the diabetic participants with current use of insulin or thiazolidinedione were excluded from the study." (PMID 25525511, 2014). "The injection of 60 mg/Kg body weight streptozotocin resulted in onset of diabetic mellitus, due to damage to pancreas thus reducing the concentrations of insulin." (PMID 24511321, 2014). "As a measure of individual beta-cell reserve for metabolic control, the time between diabetes onset and initiation of insulin substitution, i.e. the insulin-free period, was investigated in the different groups." (PMID 24580798, 2014). "The aim of this study was to measure the body composition in adults with newly diagnosed type 2 diabetes mellitus and to explore the effect of metformin therapy on the various components of body composition, insulin sensitivity, and glucose homeostasis." (PMID 25247153, 2014). "Participants averaged 8.7 years living with a diagnosis of diabetes and 8 (53.3%) participants required daily insulin injection." (PMID 25006496, 2014). "Diabetes mellitus (DM) is a group of metabolic diseases characterized by hyperglycemia, resulting from defects in insulin secretion, insulin action, or both." (PMID 24714352, 2014). "The small, but significant, improvement in glucose response in healthy individuals after only two weeks of intervention suggests a potential for the use of MOPL30 in insulin resistant individuals, or patients with diabetes." (PMID 24886291, 2014). "Diabetes mellitus is a metabolic disorder characterized by hyperglycemia due to insufficiency of secretion or action of endogenous insulin." (PMID 25598753, 2014). "Because diabetes affects hundreds of millions of people worldwide and insulin is commonly used for the control of blood glucose in patients with type 2 diabetes mellitus (T2DM), it is important to elucidate the link between T2DM/insulin use and lung cancer." (PMID 24991802, 2014). "When the cells decompensate and thereby fail to secrete adequate insulin in the face of increased hormone demand, then there, overt diabetes comes." (PMID 24672804, 2014). "Diabetes mellitus is a group of metabolic diseases characterized by hyperglycemia, impaired insulin sensitivity, and developments of diabetes-induced pathologies." (PMID 25143800, 2014). "Pathway analysis based on the differentially expressed mRNAs revealed significant pathways with P-values<0.05, including the insulin signaling pathway, type 2 diabetes mellitus, porphyrin and chlorophyll metabolism pathway." (PMID 24983625, 2014). "Progression of diabetes, including increases in blood glucose and declines in blood insulin, was observed earlier in male rats than in females, and diabetic grade was more critical in male rats." (PMID 24892034, 2014). "Recent studies have described trajectories in plasma glucose, insulin sensitivity, beta cell function, and subclinical inflammation related to diabetes before the disease is diagnosed." (PMID 24523667, 2014). "STZ induces diabetes by selectively destroying insulin producing pancreatic endocrine cells and damages kidney similar to early stage diabetic nephropathy." (PMID 25295146, 2014). "The improvement in glycaemic control in T2DM patients achieved by SGLT2 inhibition also led to the consideration to use SGLT2 inhibitors in conjunction with insulin therapy in type 1 diabetes mellitus." (PMID 25365416, 2014).